BRCA2 (BRCA2 DNA repair associated)
Diseases named in the same sentence as BRCA2 in open-access papers (continued):
Sharing a sentence is not in itself a finding about the gene and the disease.
breast cancer (continued). "For women with BRCA2 mutations, meta-analysis of seven articles found low-dose exposures from either mammography or chest X-rays led to an increase risk for breast cancer (OR = 1.3; 95% CI = .9–1.8)." (PMID 28865460, 2017). "It was not really possible to assess the 10% threshold with a Manchester score of 15–19 as only seven breast cancers that were ER− HER2+ were tested one of which (14%) had a BRCA2 mutation." (PMID 27796713, 2017). "Within the last few years, many studies have focused on the association between BRCA2 gene polymorphisms and cancer risk, including breast cancer, ovarian cancer, non-Hodgkin lymphoma, prostate cancer and others." (PMID 28418854, 2017). "Breast cancer susceptibility genes BRCA1 and BRCA2 causative variant account for only 10–20% of breast cancers with a known family history." (PMID 29093764, 2017). "Mutation detection accuracy was affected by the choice of primer handling approach based on real NGS datasets of 7 human peripheral blood or breast cancer tissue samples with known BRCA1/BRCA2 mutations and >130000 simulated NGS datasets with unique mutations." (PMID 28484262, 2017). "Inherited germline mutations affecting a single copy of the BRCA2 tumor suppressor gene predispose to cancers of the breast, ovaries, pancreas, prostate, and other organs." (PMID 28575672, 2017). "Literature review also recommends that high-risk genes other than BRCA1 and BRCA2 possibly enhance the risk of developing breast cancer, mainly for younger females." (PMID 28969709, 2017). "In this study, we analyzed the frequency of 7 BRCA1 and 25 BRCA2 variants in an Asian cohort of 2,110 breast cancer patients and 1,493 healthy women, in which the pathogenicity of variants is evaluated using a case-control approach." (PMID 28222693, 2017). "In this study, we analyzed the frequency of 7 BRCA1 and 25 BRCA2 variants from exonic and intronic regions identified previously in Malaysian breast cancer patients by germline analysis." (PMID 28222693, 2017). "Some researchers have confirmed that some splice site variants of BRCA1 and BRCA2 can produce deleterious exonic variants which have relationship with the breast cancer families." (PMID 28881705, 2017). "Increasing evidence supports the benefit of identifying BRCA1 and BRCA2 germline mutations in early breast cancer." (PMID 28120249, 2017). "In the present study, we have tried to gain molecular insights into a common genetic variant (rs804271) previously reported by our group to be associated with increased breast cancer risk in BRCA2 mutation carriers." (PMID 29383107, 2017). "A second well-known example is the Icelandic population in which one founder mutation in BRCA2 999del5 has a population carrier frequency of 0.4%, and account for 64% of breast cancer families." (PMID 29088781, 2017). "Genetic susceptibility to breast cancer comprises inherited mutations of the BRCA1 and BRCA2 genes related to hereditary breast cancers." (PMID 28761624, 2017). "Although specific mutations in BRCA1 and BRCA2 are known to be responsible for inherited susceptibility to breast cancer in families with early-onset disease, BRCA1/2 mutation carriers account for just 20% of the enhanced risk in first-degree relatives." (PMID 28569218, 2017). "Pathogenic germline mutations in BRCA1 (n = 10) or BRCA2 (n = 10) were detected retrospectively in a biobank research setting, 5–7 years after breast cancer diagnosis, in 20 out of 273 breast cancer patients." (PMID 28120249, 2017). "Women carrying mutations in BRCA1 or BRCA2 show up to 80% of increased risk for developing breast cancer, while men present up to 6%." (PMID 28651617, 2017). "Recently, PARP inhibitors were utilized to treat BRCA1 and BRCA2 mutation-associated ovarian and breast cancers." (PMID 28569838, 2017).
breast cancer (continued). "Germline mutations in the tumor suppressor genes, BRCA1 and BRCA2 account for approximately 20% of cases of hereditary breast cancer cases." (PMID 27926510, 2017). "In this work, we have constructed a 7-exon BRCA2 minigene (exons 14 to 20) where we mapped critical splicing regulatory sequences and tested 52 selected variants of exons 17 and 18 detected in breast cancer patients." (PMID 28339459, 2017). "Only 5 deleterious BRCA2 mutations in CRC were previously reported in the BIC database as germ-line mutations in breast cancer." (PMID 28591715, 2017). "This present study has demonstrated a very low frequency of detection of BRCA1 and BRCA2 mutation carriers amongst primary screens of women with HER2 amplified breast cancers, particularly those with ER+ ve tumours." (PMID 27796713, 2017). "For instance, the original item 4 read as follows: “A gene can be associated with several different traits—for example, the breast cancer gene mutation (BRCA2 gene) is associated with prostate cancer and melanoma”." (PMID 28114357, 2017). "Longer term quantitative studies are also needed to provide information about breast cancer risk to women with a BRCA1/BRCA2 mutation who are disease-free more than five years after treatment for ovarian cancer." (PMID 28780755, 2017). "We determined the spectrum of BRCA1 and BRCA2 deleterious mutations and variants in 467 breast cancer patients by full sequence analysis and large genomic rearrangement analysis." (PMID 28222693, 2017). "Genetic history has already provided such an example: BRCA1 and BRCA2 gene mutations significantly increase the risk of developing breast cancer; however, outcomes of carriers seem to be similar to those with sporadic breast cancer." (PMID 28830573, 2017). "Thirteen early-stage breast cancer patients with germline mutations in either BRCA1 or BRCA2 were treated for 2 months with talazoparib." (PMID 28454587, 2017). "Specifically, mutations in FANCD1 (BRCA2) carry an 82% lifetime risk of breast cancer, and 23% risk of ovarian cancer." (PMID 28157704, 2017). "BRCA2 or the breast cancer susceptibility gene 2 is a tumor suppressor, which when mutated increases the risk of breast cancer." (PMID 29254187, 2017). "The overall score for the association ‘BRCA2-breast carcinoma’ combines all the data type scores (somatic mutations, text mining, etc.)." (PMID 27899665, 2017). "Soon after, a second predisposing breast cancer (BC) gene was positioned at chromosome 13q12–13, BRCA2." (PMID 28858227, 2017). "Four recurrent BRCA1 mutations (c.3780_3781delAG, c.5154G > A, c.5468-1del8 and c.5470_5477del8) and two recurrent BRCA2 mutations (c.3109C > T and c.5682C > G) were identified in unrelated breast cancer patients." (PMID 26852015, 2016). "For example, a BRCA2-mutated breast cancer cell line, HCC1428, partially acquired resistance to cisplatin by a secondary genetic change in BRCA2 that rescued BRCA2 function." (PMID 27094881, 2016). "At the age of 70, cumulative cancer risk for BRCA1 and BRCA2 mutation carriers ranges from 43% to 88% for breast cancer development, and from 11% to 59% for ovarian cancer." (PMID 27015555, 2016). "The discovery of BRCA1 and BRCA2 made it for the first time possible to offer genetic testing to determine breast cancer risk." (PMID 27881737, 2016). "This suggests that breast cancers arising in BRCA2-mutation carriers have essential shared properties that drive carcinogenesis and can be targeted for intervention." (PMID 27294413, 2016). "As a consequence, little is known about the psychological feelings and psychosocial conditions of Chinese breast cancer patients who have a BRCA1 or BRCA2 mutation, leading to a significant deficiency in nursing care and intervention." (PMID 27428375, 2016). "Since the discovery of BRCA1 and BRCA2 as breast cancer susceptibility genes, much focus has been placed on discovering additional DNA variants that are associated with FBC development." (PMID 26969729, 2016).
breast cancer (continued). "BRCA2 (breast cancer early onset 2) is a widely known anti-oncogene and associated with the risk of breast cancer and ovarian cancer." (PMID 27632928, 2016). "The purpose of this pilot study is to investigate the contribution of common BRCA1 and BRCA2 mutations to early onset and familial cases of breast cancer in Uzbekistan." (PMID 29138730, 2016). "We identified 21.5% of patients harboring BRCA1/BRCA2 mutations and characterized the genetic ancestry of a sample group at-risk for hereditary breast cancer showing once again how admixed is the Brazilian population." (PMID 27741520, 2016). "Currently no specific guidelines for systemic therapy in the metastatic setting are available for BRCA1- or BRCA2-mutated breast cancers." (PMID 27323902, 2016). "This study aims to provide evidence for a clinically meaningful improvement of the experimental regimen over standard of care chemotherapy for metastatic BRCA1- or BRCA2-mutated breast cancer." (PMID 27323902, 2016). "We found that the spectrum of BRCA1 and BRCA2 germline mutations in Chinese high risk breast cancer patients are much smaller than those in Caucasian patients, and little has been recognized in this field." (PMID 26852015, 2016). "Mutation in BRCA2 also has a special significance as the mutation carriers can be diagnosed with breast cancer at lower age and has a shorter survival." (PMID 27478808, 2016). "As haplotype analysis of BRCA1 c.5470_5477del8 mutation and BRCA2 c.3109C > T mutation had been performed in Chinese high risk breast cancer patients, we performed haplotype analysis on the other four recurrent mutations in this study." (PMID 26852015, 2016). "Mutations in PALB2 are associated with increased risk of breast cancer, similar to that of BRCA2, making it an important hereditary breast cancer susceptibility gene." (PMID 27490902, 2016). "Another PARP inhibitor, Olaparib (AZD-2281, AstraZeneca), showed response in 41% of women with BRCA1- and BRCA2-deficient breast cancer in a phase 2 trial." (PMID 28025559, 2016). "BRCA1 and BRCA2 are involved in the HR repair pathway, but are mutated in familial early-onset breast cancer, rendering this pathway defective." (PMID 26784176, 2016). "The discovery of the germline mutations in BRCA1 and BRCA2 confirmed the presence of genetic predisposition for familial breast cancer." (PMID 27148484, 2016). "In all, 48 patients had a BRCA1 mutation (15 with breast cancer, 33 with ovarian cancer) and 26 had a mutation within BRCA2 (12 breast, 14 ovary)." (PMID 27002934, 2016). "Patients with mutation in BRCA2 are predisposed to breast cancer and other malignancies such as pancreatic, prostate cancer and melanoma." (PMID 27478808, 2016). "Human breast cancer susceptibility gene, BRCA2, encodes a 3418-amino acid protein that is essential for maintaining genomic integrity." (PMID 27490902, 2016). "Two patients with the deleterious mutation BRCA2 or RAD50 had male family members with breast cancer." (PMID 26824983, 2016). "Here we aimed to identify studies evaluating mutations in BRCA1 or BRCA2 genes and clinical outcome in breast cancer to assess the influence of age and hormonal receptor expression on survival." (PMID 27149669, 2016). "Heterozygous carriers of BRCA1 or BRCA2 mutations have a 82% lifetime risk of breast cancer, as well as 54 and 23% risks of ovarian cancer, respectively." (PMID 27037238, 2016). "BRCA1 and BRCA2 (with 70 and 59 variants, respectively) accounted for 39.1% of positive findings, meaning the majority of positive results identified in women with breast cancer were in genes other than BRCA1/2." (PMID 26681312, 2016). "Mutations in BRCA1 and BRCA2 genes explain approximately 15% of familial breast cancers and are the most common hereditary lesions in breast cancer." (PMID 27149669, 2016). "Following PCR amplification and sequencing of BRCA1 and BRCA2, in 10 males with breast cancer, their variants and polymorphisms were detected." (PMID 27478808, 2016).
breast cancer (continued). "It is now well established that women who carry mutations in the PALB2 gene are at similar breast cancer risks as those who carry mutations in BRCA2) making many rethink the appropriateness of the initial “moderate or intermediate risk gene” label." (PMID 27099641, 2016). "In this context we report our findings and encourage others to do the same, so as to move our knowledge on effects of interventions to prevent BRCA2-associated breast cancer death from assumptions to empirical observed effects of interventions." (PMID 27087880, 2016). "Combining the published series from Manchester and Oslo increases the number of BRCA2 mutation carriers diagnosed with breast cancer in a combined MRI/mammography programme from 20 to 34 when only women unaffected with breast cancer at entry are included." (PMID 27087880, 2016). "Genetic testing for mutations in BRCA1 or BRCA2 identifies women at a high-risk of developing breast cancer; however, to date the only highly effective primary breast cancer prevention strategy is prophylactic bilateral mastectomy." (PMID 27893411, 2016). "There are thirteen FA genes, and one of these genes is identical to the well known breast cancer susceptibility gene, BRCA2." (PMID 26967246, 2016). "One of mutations found in BRCA2 gene, c.6952C>T/p.Arg2318Ter, has previously been identified in Japanese having a strong family history of breast cancer." (PMID 27732944, 2016). "History of prior breast cancer was available for 43 cases who were either BRCA1 or BRCA2 mutation carriers." (PMID 27492892, 2016). "An example of genetic susceptibility to breast cancer includes mutations in the breast cancer 1 (BRCA1) or BRCA2 gene, which results in a lifetime risk of breast cancer of between 60% and 85%." (PMID 27582548, 2016). "The chosen design aims to provide evidence for a clinically meaningful improvement of carboplatin-olaparib followed by olaparib monotherapy over current standard therapy as first line treatment for BRCA1- or BRCA2-mutated advanced breast cancer." (PMID 27323902, 2016). "In one example, a somatic BRCA2 nonsense mutation in a breast cancer case was detected in both neoplasm and the matched adjacent non-neoplastic tissues at 23 and 2 % variant allele fractions (VAFs), respectively." (PMID 27756300, 2016). "On the contrary, male breast cancer was observed in 13 out 80 families (16 %) carrying c.5682C > G and c.8878C > T or other BRCA2 mutations of our dataset (p = 0.04907)." (PMID 26852130, 2016). "The common hereditary forms of breast cancer have been primarily attributed to the inheritance of mutations in the BRCA1 or BRCA2 genes." (PMID 26981296, 2016). "The Breast Cancer Linkage Consortium reported an increased risk of GC in BRCA2 families (RR = 2.59; 95 % CI 1.46–4.61) that was greater in carriers < 65 years old than in older carriers." (PMID 26779294, 2016). "Preclinical studies in breast cancer models showed that BRCA1 or BRCA2 deficient cell lines, when compared to BRCA proficient cell lines, are extremely sensitive to PARP1 inhibition." (PMID 27323902, 2016). "Even more prominently, inactivation of the distal FA pathway through mutations in the BRCA2 (FANCD1) gene has been reported in breast cancer (familial cases), pancreatic cancer and ovarian cancer, among others." (PMID 26843614, 2016). "The probability of an individual to carry a BRCA1 or BRCA2 germline mutation is based primarily on clinical data such as family history, age at diagnosis of breast cancer and ethnicity." (PMID 27129401, 2016). "In this study, we demonstrate a significant inverse relationship between plasma OPG levels and breast cancer risk among 206 women with an inherited BRCA1 or BRCA2 mutation." (PMID 27893411, 2016). "This pilot study aimed to investigate the contribution of BRCA1 and BRCA2 mutation to early onset and familial cases of breast cancer in Uzbekistan." (PMID 29138730, 2016).
breast cancer (continued). "We evaluated possible pathologic differences between invasive breast cancers arising in male and female BRCA2 mutation carriers by comparing available data from female mutation carriers with breast cancer in the CIMBA dataset." (PMID 26857456, 2016). "BRCA1 and BRCA2 are two tumor suppressor genes which have been proven to be breast cancer susceptibility genes." (PMID 27428375, 2016). "Intensive combined breast cancer screening with annual MRI and mammography appears to improve survival from breast cancer in BRCA2 mutation carriers." (PMID 27087880, 2016). "The association between the presence of mutations in BRCA1 and BRCA2 genes and an increased risk of developing breast cancer is well known." (PMID 27149669, 2016). "In our model, WGS correctly identified 132 women (range 121–198) with a pathogenic BRCA1 or BRCA2 mutation who would develop breast cancer." (PMID 27252788, 2016). "Another famous and well-studied founder mutation is the BRCA2 c.771del5, that is identifiable in approximately 8 % of both breast cancer and ovarian cancer Icelandic cases." (PMID 26852130, 2016). "In CMT, BRCA1, and BRCA2 have, for example, already been investigated and were associated with an increased mammary tumor risk in English Springer Spaniels." (PMID 27187374, 2016). "In contrast, in the present study, we showed that MBC associated with BRCA2 mutations presents with higher histologic grade than both breast cancer in female BRCA2 mutation carriers and MBC in the general population from SEER." (PMID 26857456, 2016). "Gene pathway analysis illustrates that CD-induced down regulation of HR was associated with decreased expression of BRCA2, a tumour suppressor gene that has been extensively linked to breast cancer development." (PMID 27014724, 2016). "Population-based family studies have provided evidence that at least some of these mutations are associated with breast cancer risk as high as those associated with rare BRCA2 mutations." (PMID 27595995, 2016). "We previously summarized the spectrum of the germline mutations in these genes and found that the BRCA1 and BRCA2 tumor suppressor genes are the two most important susceptibility genes and account for nearly 98 % of hereditary breast cancer in China." (PMID 26852015, 2016). "BRCA2 mutations are reported to be rarely associated with HER2-overexpressing advanced breast cancer and even more rarely with brain metastases at diagnosis." (PMID 27195161, 2016). "These were followed by reports from several other trials in BRCA1- and BRCA2-deficient breast cancer, ovarian cancer, melanoma, colorectal cancer, hepatocellular carcinoma, and cervical cancer." (PMID 28025559, 2016). "In the subgroup analysis, the highest overall BRCA1 and BRCA2 mutations rate was 50.0 % (8/16) in the breast cancer patients with family histories of ovarian cancer." (PMID 26852015, 2016). "Other methods of conservative care over high-risk of ovarian and breast cancer patients(BRCA1 or BRCA2 carriers) have proven ineffective." (PMID 26928677, 2016). "Mutations in the breast and ovarian cancer susceptibility genes, BRCA1 and BRCA2, are responsible for the majority of hereditary cases of breast cancer and ovarian cancer." (PMID 27229687, 2016). "For example, only 13 of the 1,791 BRCA1 variants and three of the 2,000 BRCA2 variants in the Breast Cancer Information Core (BIC) database were derived exclusively from mainland Chinese patients." (PMID 26848529, 2016). "In one study with olaparib, women with BRCA1 or BRCA2 mutations and recurrent advanced breast cancer were assigned to two sequential cohorts in a phase 2 study." (PMID 27252813, 2016). "In particular, germline mutations in breast cancer 1 (BRCA1) and BRCA2 account for 2%-10% of breast cancer cases depending on the ethnic population." (PMID 27241552, 2016).